DPP4 (dipeptidyl peptidase 4)
Diseases named in the same sentence as DPP4 in open-access papers (continued):
Sharing a sentence is not in itself a finding about the gene and the disease.
glioma (16 papers, 2017 to 2025). A benign or malignant brain and spinal cord tumor that arises from glial cells (astrocytes, oligodendrocytes, ependymal cells). "Similarly, reduced DPP4 activity in poorly differentiated gliomas and an associated decrease in Substance P processing is linked to the loss of cell growth inhibition via reduced calcium signalling." (PMID 33143089, 2020). "Analysis of TCGA data showed that glioma patients with decreased DPP4 expression had improved survival rates." (PMID 41096775, 2025). "Several reasons exist for the tumor-promoting properties of MDSCs in gliomas, and in addition to the expression of checkpoint proteins such as PD-L1, increased expression of arginase, integrin ß1 and dipeptidyl peptidase 4 (DPP-4) has also been described." (PMID 38275375, 2023). "Other upregulated factors involved in promoting glioma progression include integrin ß1, which can form complexes with multiple α-subunits, and dipeptidyl peptidase 4 (DPP-4), a serine peptidase that can cleave various substrates such as chemokines." (PMID 38275375, 2023). "In gliomas, DPP4-like enzyme activity increases with tumor more malignancy, mainly due to DPP4 and FAP." (PMID 36172198, 2022). "The Kaplan–Meier Plotter of LUSC, LUAD, KIRP, KIRC, brain lower grade glioma, and adrenocortical carcinoma further showed that DPP4 expression significantly correlated with the prognosis of specific cancer types." (PMID 33614513, 2021). "High DPP4 expression indicated a poor prognosis in some specific cancer types, including LUSC, bladder cancer, prostate adenocarcinoma, and brain lower grade glioma, and we found that the unique cancer LUSC was associated with DPP4 expression and prognosis." (PMID 33614513, 2021). "Therefore, the DPP4 inhibitor, sitagliptin, used in this study is considered a potential therapeutic option for glioma patients to overcome TMZ resistance." (PMID 39062119, 2024). "These miRNAs could play a role in limiting glioma growth through DPP4 regulation." (PMID 41096775, 2025). "This study investigates the therapeutic potential of evogliptin, a DPP4 inhibitor, both as a single agent and in combination with temozolomide (TMZ), in glioma models." (PMID 41096775, 2025). "Although glioma does express CXCL10, this is accompanied by the expression of dipeptidylpeptidase (DPP)-4, which cleaves CXCL10." (PMID 34771532, 2021). "DPP-4 blockade has been shown to increase the numbers of TILs, but when considering therapeutic blockade, it must be noted that DPP-4 also inhibits glioma proliferation independently of its enzymatic activity." (PMID 34771532, 2021). "Experimental blockade of dipeptidyl peptidase 4 (DPP4), otherwise known as a stem cell marker, led to an inhibition of the autophagic Beclin1 pathway and to an enhancement of TMZ-induced cytotoxicity in glioma cells." (PMID 39062119, 2024). "Nevertheless, in U87 glioma cells cultured with or without recombinant TGFbeta-1 for 72 h, the level of DPP4 protein and DPP4 enzymatic activity remained unchanged." (PMID 33494271, 2021).
Middle East respiratory syndrome (16 papers, 2015 to 2025). A viral respiratory infection that is caused by the MERS coronavirus (MERS-CoV), which most often manifests with moderate to severe respiratory symptoms, including productive cough and shortness of breath, which can progress to pneumonia and acute respiratory distress syndrome. "DPP-4 has been identified as a surface receptor for coronaviruses and is associated with the development of Middle East Respiratory Syndrome (MERS)." (PMID 34594302, 2021). "Additionally, the transmembrane bound DPP4 is used as a cell entry receptor by the Severe Acute Respiratory Syndrome Corona Virus (SARS-CoV) that causes Middle East Respiratory Syndrome (MERS)." (PMID 40293537, 2025). "In contrast, MERS-CoV (Middle East respiratory syndrome), the second member of the coronaviruses family, uses a different receptor for cell penetration, known as dipeptidyl-peptidase-4 (DPP-4)." (PMID 37626788, 2023). "DPP4 was described as a main receptor for the Middle East respiratory syndrome (MERS) in 2012, and during the early days of the ongoing pandemic it was described as a coreceptor able to bind to the spike protein of SARS-CoV-2." (PMID 33918318, 2021). "Genetically engineered immunoadhesin (DPP4-Fc) produced in green plants has been shown to be able to bind to MERS-CoV (Middle East Respiratory Syndrome), preventing the virus from infecting lung cells." (PMID 26633378, 2015). "The high frequencies of AKI and use of RRT in Middle East Respiratory Syndrome (MERS) may be due to the high renal expression of dipeptidyl peptidase-4, the viral receptor for MERS-CoV." (PMID 34733538, 2021). "Similarly, Middle East respiratory syndrome (MERS)-associated coronavirus were detected in bats, and required dipeptidyl peptidase 4 cell receptors for its invasion into host cells." (PMID 28883450, 2017). "In contrast, MERS-CoV was found to utilize dipeptidyl peptidase-4 (DPP-4) rather than ACE2 as its functional receptor for establishing infection in cells and causing Middle East Respiratory Syndrome (MERS)." (PMID 36674607, 2023).
multiple sclerosis (16 papers, 2006 to 2024). A progressive autoimmune disorder affecting the central nervous system resulting in demyelination. "In 2014, a study showed that only the group of patients with multiple sclerosis that responded long-term to IFNβ therapy showed similar DPP4 activity to the group of healthy controls." (PMID 39001488, 2024). "And the decreased serum concentration and activity of DPP-4 was observed in patients with multiple sclerosis." (PMID 37350750, 2023). "Abnormalities in DPP4 levels have also been observed in the autoimmune condition multiple sclerosis, the symptoms of which commonly involve chronic fatigue." (PMID 26694930, 2015).
renal cell carcinoma (16 papers, 2014 to 2025). "DPP4 has also been recently identified as a cancer stemness-related protein whose inhibition can rescue tyrosine kinase inhibitor resistance in renal cell carcinoma." (PMID 35620578, 2022).
gastric cancer (15 papers, 2011 to 2025). A primary or metastatic malignant neoplasm involving the stomach. "This hypothesis requires additional research and verification, not only in the context of cancer precursor lesions but also in gastric cancer, given that high DPP4 expression has been associated with a significant improvement in patient survival time." (PMID 37752199, 2023). "Boccardi and colleagues showed that serum DPP4 levels were decreased in gastric cancer and may serve as an early detection marker." (PMID 37907650, 2023). "The compounds with high recommendation value in the network mainly have the highest acacetin, wogonin, baicalein, Salvigenin, and Moslosooflavone value ranking of gastric cancer disease-related targets mainly NOS2, PTGS1, PTGS2, DPP4, and so on." (PMID 34421596, 2021). "We observed an increased expression of ACE2, DPP4, ANPEP, and ENPEP in renal tumor data available on TCGA followed by gastrointestinal cancers such as colorectal, pancreatic, and stomach cancer." (PMID 33330620, 2020).
osteoporosis (15 papers, 2016 to 2026). A condition of reduced bone mass, with decreased cortical thickness and a decrease in the number and size of the trabeculae of cancellous bone (but normal chemical composition), resulting in increased fracture incidence. "This opens up avenues for a novel understanding of the role of DPP-4 in the mechanisms underlying osteoporosis." (PMID 39054499, 2024). "Our findings extend these observations by demonstrating that elevated plasma DPP4 activities were closely associated with a higher proportion of osteoporosis/osteopenia in newly diagnosed type 2 diabetic patients." (PMID 33312197, 2020). "The present study revealed that elevated plasma DPP4 activity tended to be significantly associated with osteoporosis/osteopenia and the fracture risk in newly diagnosed type 2 diabetic patients." (PMID 33312197, 2020). "Correlation analyses between DPP4 activity and osteoporosis/osteopenia and fracture risk were performed." (PMID 33312197, 2020). "The present study showed for the first time that high plasma DPP4 activity was associated with the prevalence of osteoporosis/osteopenia in newly diagnosed type 2 diabetic patients (Ptrend=0.04)." (PMID 33312197, 2020). "The widespread use of DPP-4 inhibitors among patients with T2DM and advanced age, who are more predisposed to osteoporosis, underscores the need for a better understanding of the relationship between DPP-4 enzyme activity, its substrates, pharmacological inhibition, and bone metabolism." (PMID 39054499, 2024). "Thus, more large-scale human prospective studies are needed to evaluate the efficacy of Glp1r agonist or DPP-4 inhibitor in treating diabetic-associated osteoporosis." (PMID 35581617, 2022). "First, as a new oral hypoglycemic drug, DPP4 inhibitors might promote bone formation and inhibit bone absorption in addition to possessing practical hypoglycemic effects, reducing the risk of osteoporosis and fracture." (PMID 35586625, 2022). "This literature review shows that the increased DPP4 activity may indirectly promote bone resorption and inhibit bone formation, increasing the risk of osteoporosis." (PMID 35586625, 2022). "Accordingly, we set out to explore the associations of plasma DPP4 activities with osteoporosis/osteopenia and the ten-year probability of major osteoporotic fracture (MOF) and hip fracture (HF) estimated with modified FRAX in new onset type 2 diabetic patients." (PMID 33312197, 2020). "Certain medications not only effectively regulate blood glucose levels but also contribute positively to the prevention of osteoporosis, including metformin and dipeptidyl peptidase-4 inhibitors." (PMID 40014597, 2025). "RIF has also a positive impact on the activation of dipeptidyl peptidase 4 (DPP-4) inhibitors as the DPP-4 gene has been identified as an important genetic factor contributing to the progression of osteoporosis." (PMID 39507513, 2024). "This study reviews the regulation mechanisms of DPP4 on bone energy metabolism, bone immunity, and bone remodeling, aiming to provide a new target for the treatment of osteoporosis." (PMID 35586625, 2022). "The prevalence of osteoporosis/osteopenia showed an increasing trend with the increase in plasma DPP4 activity (P for the trend between quartiles = 0.04)." (PMID 33312197, 2020). "Of note, plasma DPP4 activity tended to be marginally higher in the osteoporosis group compared with the osteopenia group and normal bone mineral density group (7.7 ± 0.8 vs. 7.5 ± 0.9 and 7.3 ± 0.8 nmol/min/ml, respectively; P=0.07)." (PMID 33312197, 2020). "A pair of recent clinical studies have described the clinical implications of elevated plasma DPP4 activity in conditions such as cerebral ischemia and osteoporosis." (PMID 27654253, 2016). "In addition to their glycemic effects, DPP-4 inhibitors have the potential to decrease bone resorption, increase bone formation, and reduce the incidence of osteoporosis and fractures." (PMID 39054499, 2024).
osteoporosis (continued). "Similarly, the previous study showed a positive correlation between plasma DPP4 activity and osteoporosis in postmenopausal women with normal glucose tolerance." (PMID 33312197, 2020). "There is no conclusive evidence linking SGLT2i to fractures or osteoporosis, and risk of lower-limb amputation appears comparable to DPP-4 inhibitors, with some trend compared to GLP-1 receptor agonists, suggesting caution in patients with peripheral artery disease." (PMID 41811498, 2026). "Thus, the potential positive effect of DPP-4 inhibitors on osteoporosis and fractures may be more apparent in postmenopausal women because of higher bone remodeling." (PMID 39054499, 2024). "Middle-aged and elderly individuals with lower skeletal muscle function and BMD had higher expression levels of LEP, ADIPOQ, RBP4, DPP4 and inflammatory markers, suggesting that adipokines may play a role in the activation of inflammation and lead to the development of sarcopenia and osteoporosis." (PMID 37525169, 2023). "Thus, DPP4/CD26 could be involved in bone diseases such as osteoporosis by regulating naïve CD4+ T differentiation and the immune balance of its activated subsets." (PMID 35586625, 2022). "Our main objective was to determine whether postprandial plasma levels of glucagon-like peptide 1, glucagon-like peptide 2 and dipeptidyl-peptidase 4 activity, are associated with osteoporosis in non-diabetic postmenopausal women." (PMID 31541189, 2019). "Drugs used in these patients such as metformin, sulfonylureas, dipeptidyl peptidase-4 inhibitors (DPP4 inhibitors), insulin, and GLP-1 receptor agonists are noted to be better in terms of osteoporosis." (PMID 37680820, 2023). "Omarigliptin is a novel dipeptidyl peptidase-4 (DDP-4) inhibitor and this study proposes to probe into its possible therapeutic function against Osteoporosis by investigating its impacts on osteoblastic differentiation." (PMID 34787070, 2021). "By unraveling the complex interconnections between DPP-4, energy metabolism, and bone health, we can uncover valuable insight to guide the development of innovative treatments for conditions ranging from T2DM to osteoporosis." (PMID 39054499, 2024). "Additionally, DPP-4 exhibits an inverse correlation with BMD, suggesting a potential connection with osteoporosis." (PMID 39054499, 2024). "Although there was a positive correlation between DPP4 activity and the prevalence of osteoporosis, the trends were not statistically significant (P > 0.05)." (PMID 33312197, 2020). "Although a relationship has been demonstrated between DPP4 and osteoporosis in non-diabetic postmenopausal women there is little evidence on the association of GLP1 with osteoporosis in humans with no glucose metabolism disorder." (PMID 31541189, 2019). "In a retrospective cohort study, patients with T2DM and concomitant osteoporosis or osteopenia who used DPP-4 inhibitors and no antiosteoporotic medications were divided into two groups: those who switched to a GLP-1 receptor agonist and those who continued on a DPP-4 inhibitor." (PMID 39054499, 2024). "Finally, the present study fails to address the precise role of DPP4 in the pathogenesis of osteoporosis/osteopenia which is needed to be elucidated by the future investigation." (PMID 33312197, 2020). "Therefore, the main objective of this study was to determine whether GLP1 and also GLP2 and the enzyme responsible for metabolism, DPP4, are related to the presence of osteoporosis diagnosed according to bone mass criteria in non-diabetic postmenopausal women." (PMID 31541189, 2019).
Parkinson disease (15 papers, 2020 to 2026). A progressive degenerative disorder of the central nervous system characterized by loss of dopamine producing neurons in the substantia nigra and the presence of Lewy bodies in the substantia nigra and locus coeruleus. "The potential for DPP-4 inhibitors to be used in combination with other treatments for Parkinson’s disease is an area of interest." (PMID 40003982, 2025). "Most studies investigating the use of DPP-4 inhibitors in Parkinson’s disease treatment have shown that they suppress inflammation and apoptosis." (PMID 40003982, 2025). "Interestingly, we also discovered that these signalling pathways are activated in the high DPP4 expression group, along with other disease signalling pathways, such as Parkinson's disease." (PMID 37752199, 2023). "Furthermore, DPP4 inhibitors have demonstrated effectiveness in mitigating neuronal degeneration and improving motor function in multiple preclinical and clinical studies of Parkinson's disease." (PMID 41189279, 2025).
renal dysfunction (15 papers, 2013 to 2024). "Meanwhile, DPP-4 inhibitors are sometimes able to reduce albuminuria in T2DM patients with renal dysfunction and attenuated kidney injury in induced diabetic rats." (PMID 37532063, 2023). "The mean reduction in HbA1c concentration was similar to that with DPP-4 inhibitors in patients with renal dysfunction." (PMID 32317005, 2020). "It is therefore relatively easy to use DPP-4 inhibitors safely in the elderly and patients with renal dysfunction." (PMID 28490337, 2017). "Most studies focusing on DPP-4 inhibitors and renal function did not indicate any renoprotective effects of DPP-4 inhibitors; however, these reports clarified the safety and tolerability of DPP-4 inhibitors in patients with renal dysfunction." (PMID 29187821, 2017). "So far, however, research on the use of DPP-4 inhibitors in patients with renal dysfunction or albuminuria has been limited." (PMID 23570327, 2013). "DPP-4 inhibitors when GFR <50 ml/min are broadly contraindicated (or the dose should be adjusted) but linagliptin can be used at all stages of renal dysfunction." (PMID 23841986, 2013). "It is worth noting that the majority of patients infected with SARS-CoV-2 also had renal dysfunction, which might be explained by the high expression of DPP4 in the kidney and urinary system." (PMID 33614513, 2021). "DPP-4 inhibitors are known to exert hypoglycemic action even with renal dysfunction." (PMID 28725273, 2017). "Although the patient had good glycemic control for the 10 years after starting treatment with a DPP-4 inhibitor, renal dysfunction progressed over time, and the appearance of skin lesions led us to speculate that the skin and renal lesions might be related to DPP-4 inhibitor treatment." (PMID 38055184, 2024). "Furthermore, we used linagliptin in the present study, because linagliptin has a unique xanthine-based structure and takes the advantage of being used in patients with renal dysfunction without dose adjustment in contrast to other approved DPP-4 inhibitors." (PMID 25471116, 2014).